IL6 (interleukin 6)
Diseases named in the same sentence as IL6 in open-access papers (continued):
Sharing a sentence is not in itself a finding about the gene and the disease.
chronic kidney disease (continued). "The positive correlation between MPO, CU/Zn SOD and IL-6 and eryptosis levels in our study population highlights the role of oxidative stress and inflammatory cytokines in the pathogenesis of RBCs’ programmed death in patients with chronic kidney disease." (PMID 36498741, 2022). "Previous studies also reported that IL-6 was elevated in most end-stage renal disease (ESRD) patients and may play a central role in the pathophysiology of inflammation in patients with ESRD, which was related with mortality." (PMID 35386695, 2022). "A trial evaluating the reduction in inflammation in patients with advanced chronic renal disease using antibody-mediated IL-6 inhibition (RESCUE) is an ongoing phase II trial intended to demonstrate the cardiovascular benefit of IL-6 inhibition by ziltivekimab." (PMID 35054989, 2022). "Chronic kidney disease (CKD) is associated with low-grade inflammation that activates nuclear factor–κB (NF–κB), which upregulates the expression of numerous NF–κB responsive genes, including the genes encoding IL-6, ICAM-1, VCAM-1, and MCP-1." (PMID 36012158, 2022). "A study showed that patients with chronic kidney disease with lower eGFR levels had higher levels of plasma IL-1 β, IL-1RA, IL-6, TNF-α, hypersensitive CRP, and fibrinogen and that the inflammation score was inverted with GFR estimates and urinary albumin/creatinine ratio (UACR)." (PMID 34992536, 2021). "Results of the Chronic Renal Insufficiency Cohort (CRIC) showed that higher FGF23 levels are associated with higher levels of the inflammatory markers CRP, IL6, TNFα, and fibrinogen and with a higher odds ratio for severe inflammation independent of mineral metabolism and renal function." (PMID 34208131, 2021). "Moreover, the blockade of ETA-R signalling was shown to reduce IL-6 expression in a rat model of chronic kidney disease." (PMID 34769227, 2021). "Indeed, EET-A has previously been demonstrated to decrease renal inflammatory cell infiltration and levels of monocyte chemoattractant protein-1 (MCP-1), TNF-α, IL-6, and IL-1β in acute and chronic kidney disease models." (PMID 33801911, 2021). "In addition, in the progression of chronic kidney disease, serum levels of visfatin were found to be closely correlated with IL-6 and common carotid arteries intima-media thickness." (PMID 31367237, 2019). "Additionally, we summarize the roles of IL-6 in several renal diseases, such as IgA nephropathy, lupus nephritis, diabetic nephropathy, acute kidney injury, and chronic kidney disease." (PMID 28484449, 2017). "IL-6 is one of the most studied cytokines in chronic kidney disease." (PMID 28164733, 2017). "One study found that patients with chronic kidney disease exhibited increased expression of IL-6." (PMID 28358817, 2017). "In addition, in chronic kidney disease, serum levels of inflammatory markers, such as IL-6, IL-8, IL-1β, are increased." (PMID 28542419, 2017). "Thus, combined consumption of white wine and extra-virgin olive oil for two weeks decreased the plasma levels of CRP and IL-6 both in patients with chronic kidney disease and healthy individuals." (PMID 27077879, 2016). "In addition, the authors also observed increased IL6 expression levels in kidney biopsies of chronic kidney disease patients compared to age-matched control biopsies." (PMID 23883183, 2013). "Stratification analyses for microalbuminuria, macroalbuminuria and end-stage renal disease (ESRD) were also conducted for five variants: Ins/Del variant at ACE gene; SNP rs2268388 at ACACB gene; SNP rs1799987 at CCR5 gene; SNPs rs1800795 and rs1800796 at IL-6 gene." (PMID 40116328, 2025). "Studies have tied various pro-inflammatory molecules (e.g. tumor necrosis factor-alpha (TNF-α), interleukins 1β and 6 (IL-1β, IL-6) etc.)to the onset of chronic kidney disease (CKD)." (PMID 39469576, 2024).
chronic kidney disease (continued). "Several biomarkers of inflammation including IL-6, IL-1β, IL-1 receptor antagonist, CRP, TNF-α, and fibrinogen were directly associated with albuminuria and inversely associated with the measures of kidney function in the Chronic Renal Insufficiency Cohort (CRIC) study." (PMID 37840653, 2023). "Chronic kidney disease (CKD) associates an inflammatory process marked by inflammatory cytokines such as blood MCP-1 and IL-6 and C-reactive protein to albumin ratio in serum." (PMID 35735634, 2022). "Higher IL-6 levels were independently correlated to the risk of major adverse cardiovascular events (MACE), and elevated IL-6 level was associated with an increased risk of MACE at normal kidney function, mild chronic kidney disease (CKD), and moderate to severe CKD." (PMID 35845045, 2022). "In a large cohort of patients with chronic kidney disease (the Chronic Renal Insufficiency Cohort—CRIC—study), faster progression of kidney insufficiency was shown to be positively associated with chronic inflammation and increased inflammatory markers, including interleukin 6 and TNFα." (PMID 34827620, 2021). "Subsequent Cox regression analyses revealed that IL-6 (HR, 1.114), together with pre-existing chronic kidney disease (CKD), increased NLR, and decreased PTA, was the independent predictor for fatal outcome in the severe group." (PMID 33693017, 2021). "Interestingly, patients with chronic kidney disease who require high‐dose erythropoietin were found to have higher levels of circulating pro‐inflammatory biomarkers IL6 and CRP that may translate to higher levels of VTE." (PMID 35847693, 2020). "Among them, tumor necrosis factor alpha (TNF-α), interleukin-6 (IL-6), neopterin, ferritin, C-reactive protein (hs-CRP) and the complete blood count changes are considered as most valuable predictors of all-cause mortality risk from CVD events in chronic renal insufficiency conditions." (PMID 30617956, 2019). "Ang II enhanced IL-6 levels in the kidneys with profibrotic and ET-1 gene expression induction, suggesting a possible role in chronic kidney disease (CKD)." (PMID 31186952, 2019). "Numerous studies have reported an association between markers of inflammation like CRP, IL-6, TNF-α and fibrinogen and chronic kidney disease (CKD)." (PMID 28494192, 2017). "The chronic kidney disease group exhibited elevated serum urea and creatinine and reduced eGFR, along with increased levels of KIM-1, NGAL, IL-18, TNF-α, IL-6, NF-κB, and FMO3." (PMID 40978750, 2025). "IL-6 in combination with TNF-α facilitates the calcification of vascular cells to induce persistent low-grade systemic inflammation in chronic kidney disease (CKD) and progression of exacerbated diabetic nephropathy (DN)." (PMID 40733185, 2025). "Multivariable linear regression model examining IL-6 (pg/mL) and ADMA (pg/mL) as independent predictors of NT-proBNP (pg/mL) levels in patients with chronic kidney disease (n = 100; ADMA available in 52 patients)." (PMID 41450363, 2025). "Monocytes from end-stage renal disease (ESRD) patients have increased ALOX5 expression and after 6 days training, they exhibit enhanced TNF-α and IL-6 production to lipopolysaccharide (LPS)." (PMID 38980302, 2024). "While immune cells are mainly responsible for circulating IL-6 levels under homeostatic conditions, the kidneys become a major cytokine source in pathophysiological situations associated with acute kidney injury (AKI) or chronic kidney disease (CKD)." (PMID 39723211, 2024). "Overproduction of proinflammatory cytokines (such as IL1, IL6, or TNF alpha) and reactive oxygen species in patients with chronic kidney disease is mediated by the activation of monocytes and macrophages." (PMID 38921685, 2024). "Several kidney cells including podocytes and mesangial cells can produce IL-6, TGF-ß1 and IL-10 and elevated levels of such cytokines have been demonstrated in several chronic kidney diseases." (PMID 38304433, 2024).
chronic kidney disease (continued). "One study of chronic kidney disease revealed higher systemic inflammatory marker levels, such as C-reactive protein (CRP), interleukin (IL)-6, and tumor necrosis factor-α, in patients with low GNRI scores than those with high GNRI scores." (PMID 37799767, 2023). "The elevated IL-6 levels in bacteremia patients may be attributed, in part, to the higher rate of chronic kidney disease in this group, as it is well-known that CKD patients tend to exhibit increased IL-6 production and decreased clearance." (PMID 37768395, 2023). "For example, the IRE1α axis of the UPR was shown to drive acute-to-chronic kidney disease transition in tubular cells by activating JNK signaling and by increasing IL-6 and MCP1 production and secretion in an in vivo model of renal ischemia/reperfusion." (PMID 36902344, 2023). "In the case of AKI and chronic kidney disease (CKD), IL-6 increases fibroblast growth factor 23 levels, which may contribute to phosphaturia and hypophosphatemia, thus affecting renal function." (PMID 37010812, 2023). "A clinical study showed an improvement in the renal function in patients with chronic kidney disease after Lac-B administration through decreasing of serum levels of TNF-α and IL-6." (PMID 36499631, 2022). "It reduced interleukin 6 (IL-6) and tumor necrosis factor-α (TNF-α), and played an important role in oxidative stress in a rat model of chronic renal failure." (PMID 36497603, 2022). "Gender, age, BMI, course of disease, FPG, glycosylated hemoglobin, BUN, Scr, IL-6, MCP-1, and NF-κB were used as single factors, and the occurrence of end-stage renal disease was the end point." (PMID 35756496, 2022). "ANP has been identified recently as being associated with chronic kidney disease (CKD) without diabetes through the stimulation of secretion of cytokines (IL-6, TNF-α) and adiponectin." (PMID 35466213, 2022). "Effects of Shenkang injection (SKI) on the levels of CRP, IL-1β, IL-6, TNF-α, IL-4,and IL-10 in serum of chronic renal failure rats*." (PMID 35674582, 2022). "Patients with end stage renal disease (ESRD) have high circulating levels of inflammatory markers such as CRP, IL-6, TNFα, and IL-1α1,2." (PMID 33536542, 2021). "The IL-6/JAK/STAT3 signaling is hyperactivated and therefore is a good target in several cancers, chronic kidney diseases, and cardiovascular diseases." (PMID 34067609, 2021). "Treatment with an IκB kinase inhibitor attenuated sepsis-induced cardiac dysfunction with chronic kidney disease (CKD) via reduced expression of inflammatory cytokines (TNF-α, IL-1β, IL-6, and IL-10)." (PMID 32581829, 2020). "In concomitance, the diabetic patients with end-stage renal disease also showed higher levels of serum inflammatory cytokines TNF-α, IL-6, and IFN-γ." (PMID 33442388, 2020). "In the end stage renal disease (ESRD) patients, the therapeutic hemodialysis and peritoneal dialysis per se further stimulate inflammatory responses and increase IL-6 production." (PMID 28484449, 2017). "Serum IL-6 is often increased in NTIS, and the serum level of this cytokine is inversely correlated with that of T3 in patients with end stage renal disease (ESRD)." (PMID 25174507, 2014). "Recently, ziltivikimab, an IL‐6 inhibiting monoclonal antibody, has been tested in the RESCUE trial amongst participants with moderate to severe chronic kidney disease and an hs‐CRP levels of > 2.0 mg/L, where treatment for 12 weeks resulted in 77%–92% reduction in the median CRP levels." (PMID 40309624, 2025). "Moreover, patients with chronic kidney disease (CKD) exhibit significantly reduced Klotho levels accompanied by elevated inflammatory cytokines, including interleukin-6 (IL-6) and tumor necrosis factor-alpha (TNF-α)." (PMID 40519908, 2025).
chronic kidney disease (continued). "While methylprednisolone use and chronic kidney diseases were significant predictors of mortality in the anti-TNF group, no traditional baseline characteristics independently predicted mortality in the anti-IL6 group, except the final therapy received." (PMID 40700294, 2025). "Potential of this IL‐6 inhibitor in reduction of CRP and MACE rates amongst patients with cardiovascular disease, chronic kidney disease and baseline hs‐CRP levels of > 2.0 mg/L, is currently being tested in the ZEUS trial; results of which are highly anticipated." (PMID 40309624, 2025). "Additionally, IL-6 elevates serum fibroblast growth factor 23 (FGF23) levels via sIL-6R, promoting the development of acute and chronic renal failure." (PMID 39749325, 2024). "IS, a bacterial metabolite of tryptophan, exhibits pro-inflammatory effects in chronic kidney disease (CKD) patients: it increases inflammatory cytokines (TNF-α, IL-6, and TGF-β1) and ROS levels in C2C12 cells, accelerating skeletal muscle atrophy and negatively affecting muscle strength." (PMID 38891777, 2024). "In a cohort of patients with baseline chronic kidney disease, African American individuals had significantly higher levels of circulating IL-6 levels compared to Mexican American and non-Hispanic (NH) White individuals." (PMID 39077632, 2024). "Although this study examined only patients with kidney disease, it may be possible that EV-induced blockage of IL-6 arises in PwCF infected with SARS-CoV-2, since inflammation is central to the pathogenesis of CF and chronic kidney disease." (PMID 38612524, 2024). "Common comorbidities, including obesity, diabetes, hypertension, chronic obstructive pulmonary disease (COPD), and chronic kidney disease (CKD), have been postulated to drive the systemic inflammatory state, as shown by elevated levels of circulating cytokines, including IL-1β, IL-6, CRP, and TNFα." (PMID 36818566, 2023). "In a trial conducted for 12 weeks on early chronic kidney disease, there were no changes in IL-6 levels." (PMID 36904187, 2023). "In addition, treatment with melanin prevented adenine-induced chronic renal failure in mice and cisplatin-mediated nephrotoxicity by suppressing MAD, upregulating GSH, SO, GPx, and CAT, and inhibiting the production of TNF-α and IL-6." (PMID 36838869, 2023). "Several traditional inflammatory cytokines, such as C-reactive protein (CRP), interleukin-6 (IL-6), and tumor necrosis factor-α (TNF-α), have been reported to aggravate kidney function impairment and increase the risk of death in patients with chronic kidney disease (CKD) and MHD." (PMID 37724554, 2023). "Eligible patients with end-stage renal diseases showed significantly higher serum IL-6, MCP-1, and NF-κB levels versus those without end-stage renal diseases (P < 0.05)." (PMID 35756496, 2022). "In the Chronic Renal Insufficiency Cohort (CRIC) study, an inverse relationship between biomarkers of inflammation (interleukin-1β, interleukin-1 receptor antagonist, interleukin-6, tumor necrosis factor-α, C-reactive protein, and fibrinogen) and renal function was advocated." (PMID 33466271, 2021). "A study conducted in patients with chronic renal insufficiency revealed that kidney injury was positively correlated to the levels of proinflammatory cytokines, namely, tumor necrosis factor alpha (TNF-α) and interleukin-6 (IL-6) in the plasma." (PMID 32292787, 2020). "Additional inflammatory cytokines such as PlGF contributes to cardiac hypertrophy through IL-6 signaling and it is a predictor of increased left ventricular mass in non-hemolytic diseases such as chronic kidney disease." (PMID 32973791, 2020). "The Chronic Renal Insufficiency Cohort (CRIC) study found an inverse correlation between renal function and inflammatory biomarkers (IL-1β, IL-1 receptor antagonist, IL-6, TNF-α, C-reactive protein, and fibrinogen) as well as a direct relationship between kidney disease and albuminuria." (PMID 32823917, 2020).
chronic kidney disease (continued). "A large number of recent studies has established a central role of the profibrotic cytokine TGF-β1 and the proinflammatory cytokine IL-6 for TH17 cell differentiation and secretion of IL-17 and shown that both are markedly involved in pathogeneses of acute and chronic kidney disease." (PMID 27243813, 2016). "Additionally, clinical studies have demonstrated that calcitriol treatment suppressed IL-6 and TNF-α expression in patients with chronic kidney disease." (PMID 25823676, 2015). "Although markedly elevated plasma concentrations of proinflammatory cytokines, such as IL-6, have been documented in most ESRD patients, the origin of inflammation in patients with chronic renal disease remains unclear." (PMID 25068056, 2014). "In chronic kidney disease receiving hemodialysis, when compared with placebo, curcumin had a non-significant effect on IL-6 (SMD:0.24%; 95% CI: 0.14, 0.62; I2 = 97.1%), TNF-a (SMD:0.11; 95% CI: 0.19, 0.40; I2 = 95.9%) or hs-CRP (SMD: 0.17%; 95%CI: 0.36, 0.03; I2 = 79.6%)." (PMID 40538540, 2025). "IL-6: Interleukin-6; ADMA: asymmetric dimethylarginine; NT-proBNP: N-terminal pro–B-type natriuretic peptide; SD: standard deviation; CKD: chronic kidney disease." (PMID 41450363, 2025). "For example, in chronic kidney disease (CKD), the increased expression of GPR68 on human monocytes promotes the release of TNF-α, IL-6, and other pro-inflammatory cytokines, which aggravate systemic inflammation and fibrosis." (PMID 41190345, 2025). "We found increased levels of IL-6, IL-8, CD40, PDL-1, FGF-23, IL-15-RA, TGF-a, and CCL25 that persist at two months after LTA in IKF patients, consistent with current concepts of inflammation as a crucial pathophysiological mechanism in the development of chronic kidney disease." (PMID 39440014, 2024). "Proinflammatory cytokines such as TNFα, IL-1β, and IL-6 are potent stimuli for the FGF-23 secretion by osteocytes and have been demonstrated to play a role in upregulating intact FGF23 in experimental models in vivo of both acute kidney injury and chronic kidney disease." (PMID 37893926, 2023). "Plasma levels of interleukin (IL)-1β, IL-1 receptor antagonist (IL-1RA), IL-6, tumor necrosis factor (TNF)-α, transforming growth factor (TGF)-β, high-sensitivity C-Reactive protein (hs-CRP), fibrinogen and serum albumin were measured in 3,939 Chronic Renal Insufficiency Cohort study participants." (PMID 25909952, 2015). "However, when subjects with reduced renal function were excluded from the analysis, only sTNF-R1 and Interleukin 6 (IL-6), but not CRP, remained positively associated with incident chronic kidney disease." (PMID 25259714, 2014). "The stimulation of IL-6 by uremic toxins and the inhibitory effects induced by specific siRNA were consistent with the results from EMSA, which further confirmed that the uremic toxins play pivotal roles in the inflammatory responses of patients with chronic renal failure." (PMID 25174507, 2014). "IL-6: interleukin-6; ADMA: asymmetric dimethylarginine; NT-proBNP: N-terminal pro–B-type natriuretic peptide; SE: standard error; CI: confidence interval; CKD: chronic kidney disease." (PMID 41450363, 2025). "Patients with chronic kidney disease (CKD) display higher serum levels of oxLDL, characterized by an hyperinflammatory phenotype of monocytes accompanied by an increased production of pro-inflammatory cytokines (i.e., TNF-α, IL-1β and IL-6)." (PMID 36979747, 2023). "Inhibition of interleukin 6 (IL‐6) signalling has been proposed as a potential cardioprotective strategy for patients with chronic kidney disease (CKD), but the direct effects of IL‐6 inhibition on renal function are not known." (PMID 33393675, 2021). "An amount of 15% w/w orally in the feed of flaxseed for 33 days significantly reduced the renal inflammation (IL-1β, IL-6, and NF-κB) in STZ-induced diabetic rats with or without chronic kidney disease." (PMID 37685162, 2023).